TNF (tumor necrosis factor)
Diseases named in the same sentence as TNF in open-access papers (continued):
Sharing a sentence is not in itself a finding about the gene and the disease.
Granuloma (349 papers, 2005 to 2026). A compact, organized collection of mature mononuclear phagocytes, which may be but is not necessarily accompanied by accessory features such as necrosis. "In-vitro data further show that tapinarof attenuates LL-37–driven mast-cell degranulation and decreases MMP-9, TNF-α, and IL-6, all implicated in granuloma formation and dermal remodeling." (PMID 41451029, 2026). "Beyond its Th17-suppressive and skin-barrier-restorative activities, tapinarof directly dampens LL-37-induced mast-cell degranulation, down-regulating chymase-1, tryptase-β, MMP-9, TNF-α and IL-6—mediators implicated in granuloma formation." (PMID 41451029, 2026). "In mouse models of visceral leishmaniasis, as well as in dogs and humans, TNF-α appears to play a critical role in the onset of granuloma formation, which is associated with the control of L. infantum infection." (PMID 39963187, 2025). "The patients even had well-formed tissue granulomas in response to M. tuberculosis, in contrast to TNF-deficient mice infected with M. tuberculosis or mice on anti-TNF treatment infected with BCG40,56,57." (PMID 39198650, 2024). "Proinflammatory cytokines such as TNF-alpha and IL-1 are released by immune cells within granulomas, which then attract more immune cells and cause an inflammatory reaction, resulting in chronic inflammation, scarring, tissue damage, and systemic symptoms." (PMID 39371894, 2024). "IL-6 and TNFα have been associated with the formation of granuloma and chronic wasting syndrome in paratuberculosis but their role is not yet clearly defined." (PMID 38399810, 2024). "TNF-α is known to be necessary for the formation of a well-organized granuloma and host protection, as confirmed by the higher risk of developing TB disease and disseminated infection in subjects who underwent anti-TNF-α treatment." (PMID 37662901, 2023). "TNF‐α is also associated with granuloma biogenesis and integrity, driving the formation of durable solid granulomas." (PMID 37674971, 2023). "The class-II major histocompatibility complex factor HLA-DRA (human leukocyte antigen DR isotype) is a downstream effector of interferon-γ and TNF-α stimulations and has been recently implicated in granuloma formation in cutaneous sarcoidosis." (PMID 38067175, 2023). "The treatment of these in vitro granulomas with immunosuppressing anti-tumor necrosis factor-alpha (TNF-α) monoclonal antibodies caused the resuscitation of M. tuberculosis in the same way that it does in infected humans." (PMID 36557586, 2022). "Overall, the choice of TNF inhibiting agent has been shown to impact susceptibility to M. tuberculosis infection by interfering with granuloma formation." (PMID 36159650, 2022). "Amongst type 1 cytokines, IFN-γ and TNF have been most closely associated with Mtb pathogenesis and granuloma formation." (PMID 35320930, 2022). "DEM treatment was also associated with an increase in IL-6, TNF-α and ill-formed granulomas in infected mice." (PMID 35371562, 2021). "During mycobacterial infection, TNF-α deficient mice develop necrotic granulomas, pathogenic lesions which are also characteristic of the C3HeB/FeJ mice." (PMID 34083546, 2021). "Interferon-γ (IFN-γ) and TNF-α play a key role in the anti-Mtb cytokine cascade, as they are associated with the formation and maintenance of granulomas." (PMID 34835417, 2021). "TNF-RI is a receptor for the pro-inflammatory cytokine TNF-α, which is associated with chronic human schistosomiasis and contributes to granuloma formation." (PMID 33861768, 2021). "Pro-inflammatory cytokines, especially TNF-α, IL-6, IL-1β, and IL-8, not only induce inflammation but also cause leukocyte infiltration, granuloma formation, and tissue fibrosis." (PMID 34681651, 2021). "Treatment of these granuloma-like structures with adalimumab, an anti-TNF-α monoclonal antibody, reduces levels of both TNF-α and miR-889-5p and causes granuloma destruction and LTBI reactivation." (PMID 32987746, 2020).
Granuloma (continued). "As the alteration in granuloma formation was related to TNF deficiency, we investigated the activation status of granulomatous cells in individuals who formed granulomas." (PMID 32411623, 2020). "In patients with severe sepsis, the defective in vitro formation of granulomas is associated to monocytopenia and a reduced production of TNF." (PMID 32411623, 2020). "Other than IFN-γ and TNF-α, the presence of IL-6 and IL-23 have been associated to formation and maturation of granulomas." (PMID 33312173, 2020). "Adalimumab (anti-TNF-α monoclonal antibody) treatment reduced levels of both TNF-α and miR-889 and caused granuloma destruction and LTBI reactivation." (PMID 31992621, 2020). "Once patients entered LTBI status, the upregulation of miR-889 was associated with TNF-α levels and granuloma formation to maintain mycobacterial survival." (PMID 31992621, 2020). "The C3 cleavage fragments modulate CXCR4-mediated response; TNF-α, which stimulates the production of C3, is also important in granuloma formation; and its neutralization results in the loss of granuloma structure." (PMID 32344637, 2020). "MAIT cells can produce considerable amounts of cytokines, such as IFN-γ and TNF-α, which are strongly associated with granuloma formation in sarcoidosis." (PMID 31515495, 2019). "TNF-α plays a major role in defence against infection and in the formation and maintenance of granulomas; therefore, treatment with TNF-α inhibitors is recognized as a risk factor for TB." (PMID 31608149, 2019). "In an attempt to understand the relationship of local inflammatory responses and TG accumulation in foamy macrophages, we established an association between high TNFα expression and appearance of TG-rich foamy macrophages in guinea pig granulomas." (PMID 30018616, 2018). "Anti-TNF therapy has also been implicated in the susceptibility to tuberculous infection, due to the role of TNF in the formation of granulomas." (PMID 30065229, 2018). "As granuloma formation and maintenance has been associated with the release of TNF-α and IL-6 in M. tuberculosis, we assessed the presence of these cytokines in the supernatants of infected macrophages." (PMID 27757105, 2016). "As TNF is associated with granuloma formation, we measured its release by PBMCs from septic patients." (PMID 27441846, 2016). "In our study, granulomas that had a higher proportion of T cells producing IL-10 in combination with T cells producing pro-inflammatory cytokines IL-2, TNF or IL-17 were associated with sterilization." (PMID 25611466, 2015). "Reports of TNF-α inhibitors induced sarcoidosis, paradoxically describe etanercept as being more commonly associated with granuloma development, possibly because of incomplete TNF-α blockage." (PMID 25494723, 2014). "Treating granulomas with an immunosuppressant anti-TNF-α monoclonal antibody caused reactivation of dormant M. tuberculosis." (PMID 24967387, 2014). "Anti-TNF agents cause death of cells expressing TNF and disrupting granulomas which lead to reactivation of granulomatous disease." (PMID 25431725, 2014). "It has been shown that TNF-α is important for the organization and maintenance of granulomas and the associated host response in animal models of Mtb infection." (PMID 23958185, 2013). "Once recruited, TNF-α is needed for leukocyte adhesion, since an abrogation of tightly formed granulomas in TNF-α-deficient mice is observed following mycobacterial infection." (PMID 24339826, 2013). "TNFα was thought to play a central role in tuberculous granuloma formation as TNFα deficient mice showed poor granuloma formation." (PMID 23745122, 2013). "In chimeric mouse models, deletion of the variable macrophage-TCRαβ or TNF is associated with structurally compromised granulomas of pulmonary tuberculosis even in the presence of intact T cells." (PMID 22114556, 2011).
Granuloma (continued). "We found that granuloma-induced mechanical allodynia was associated with increased expression of the pro-inflammatory markers TNF-α, NGF and COX-2 in the DRGs." (PMID 21219627, 2011). "iNOS expression patterns were largely within the confinement of granuloma lesions in WT mice in contrast to TNF−/− mice where the pattern was dispersed and associated with the diffused granuloma lesions analyzed 133 days post-infection." (PMID 22132068, 2011). "The Th1 cytokines, INF-γ and TNF-α can classically activate macrophages to produce NOS-2 which in mice is associated with smaller granulomas and less fibrosis." (PMID 20663176, 2010). "Early in the acute phase of infection, the Th1 response is predominant in patients and is characterised by high levels of INF-γ and TNF-α, and is associated with large granulomas around the eggs in the liver." (PMID 20663176, 2010). "Necrotic granulomas were more evident in HIV positive patients with a clear association between TNF-α and necrosis." (PMID 19156215, 2009). "Most granuloma-associated lymphocytes have a Th1 phenotype, secreting cytokines, including interferon gamma, interleukin (IL) -2, IL-12, and tumor necrosis factor-alpha (TNF-α), which is likely to favor the granulomatous response at sites of disease activity." (PMID 18811966, 2008). "The expression of mutated membrane TNF confers protection against acute mycobacterial infection with initial control of mycobacterial growth and normal granuloma development in the lung." (PMID 16285886, 2005). "TNF-deficient animals also showed continued induction of other factors important in granulomas, such as host matrix metalloproteinase 9 (MMP9), which is highly expressed in the epithelioid population of mycobacterial granulomas and is necessary for their formation and maturation." (PMID 40304497, 2025). "Granuloma formation is significantly dependent on the production of the pro-inflammatory cytokines IFN-γ and tumor necrosis factor-alpha (TNF-α) from T cells, as studies have shown an increased susceptibility to TB and loss of granuloma structure in humans treated with TNF-α inhibitors." (PMID 39457551, 2024). "Granulomas, the hallmark pathology of chronic sarcoidosis, are composed primarily of macrophages derived from circulating blood monocytes, activated by pro-inflammatory cytokines including TNF and IL-6." (PMID 39284999, 2024). "TNF is associated with granuloma formation which is seen in both GCA and TAK arteries." (PMID 38125643, 2023). "Various cytokines, including TNF, which is induced by imatinib, regulate cell death and survival pathways, and have been implicated in host control of Mtb infections and granulomas in humans." (PMID 37200402, 2023). "Additionally, a polymorphism in TNF (the TNF+488A allele) had been noted in a CVID subset characterized by granulomas, splenomegaly, lymphopenia, reduced CD4+CD45RA+ T cells, and expanded CD8+CD57+ lymphocytes." (PMID 35359997, 2022). "More studies should be conducted to investigate whether the observed increases in cytokines IFN-γ, TNF-α, IL-2, and decrease in IL-10 found in granuloma supernatants is indeed the cause of the decreased burden of mycobacterial." (PMID 34150674, 2021). "Postoperative anti‐tumour necrosis factor (anti‐TNF) therapy might lower recurrence rates whilst the presence of mesenteric granulomas has been postulated to increase the risk." (PMID 31393663, 2020). "As the defective formation of granulomas in infected patients may be associated with a decrease in inflammatory cytokines, we measured the release of TNF and IL-10 by cells incubated with BCG-coated beads for 1 and 3 days." (PMID 32411623, 2020). "TNF-α plays a major role in causing intestinal inflammation, and its role is to accumulate inflammatory cells to the local tissues of the inflammation, cause edema, activate coagulation cascade, and form granuloma." (PMID 30075775, 2018).
Granuloma (continued). "MWCNT entering the airways of mice have been shown to elicit several pro-inflammatory events that originate from their activation of the NLRP3 inflammasome and are associated with the induction of IL-6, TNF-α, and IL-1β, formation of granulomas and development of airway fibrosis." (PMID 29922162, 2018). "Moreover, pro-inflammatory proteins, such as LTA4H, were highly expressed in caseous regions of the granuloma compared with cellular regions and associated with TNF-α expression." (PMID 27822210, 2016). "Taken collectively, these results indicate that TNF is principally produced by macrophages following infection with both Mabs variants, from very early phagocytosis after infection to later time points when the characteristic granulomas have appeared." (PMID 27806130, 2016). "Thus, the partial deficiency of IL-12, IFN-γ, and TNF-α induction in Jα18-/- mice could be responsible for a similar mechanism, since the granulomas observed in these mice were less abundant and less well-organized than in WT mice." (PMID 22457760, 2012). "We therefore postulate that, in our studies, the dependence of IL-12p70 synthesis on autologous TNF mediated signaling by antigen presenting cells such as macrophages which are mostly located within granulomas may eventually have been compromised in Tm-TNF deficient mice." (PMID 22132068, 2011). "Collectively, these findings suggest that TNF-α and NO production in MAP-associated granulomas occur independently of NOD signaling." (PMID 40433460, 2025). "Similar to TNFα, IFNγ enhances the anti-mycobacterial ability of macrophages and plays an important role in granuloma development." (PMID 39918314, 2025). "In granulomas in which necrosis takes place, TNF levels are higher compared to those in which necrosis does not take place." (PMID 40427602, 2025). "One week following DCF administration, blood TNF-α levels were significantly reduced (* p < 0.05, 95% CI for the difference: [−385.62, −302.70]) compared to the granuloma Control group." (PMID 40430898, 2025). "Immunomodulators such as methotrexate and azathioprine act by reducing T-cell proliferation and cytokine release, while TNF-α inhibitors (e.g., infliximab) specifically block TNF-α signaling, a key driver of granuloma persistence." (PMID 40225494, 2025). "Immunosuppressive therapy suppresses TNF-α and interferon-γ–mediated immune responses, impairing granuloma integrity and allowing reactivation or spread of Mycobacterium tuberculosis." (PMID 41278184, 2025). "Lymphotoxin and tumor necrosis factor-alpha (TNF-α), which are involved in disease pathogenesis due to their essential role in granuloma formation, the synthesis of IgG1 and IgG3 by plasma cells, and the ability to activate T-cell cytotoxicity." (PMID 40880768, 2025). "Granuloma formation in CS is driven by an exaggerated T-helper (Th1) immune response, characterized by elevated levels of TNF-α, IL-2, and IFN-γ." (PMID 40225494, 2025). "TNF-α plays an important role in the formation of granulomas that are crucial for containing bacterial spread in the body." (PMID 39854270, 2025). "It has been demonstrated that TNF-alpha plays a vital role in the host defence mechanism against Mycobacterium tuberculosis and in the formation of granuloma that limits the spread of infection." (PMID 40557175, 2025). "First, TNF is essential for the formation and maintenance of granulomas, which serve as immunological barriers to contain latent bacilli." (PMID 40427602, 2025). "The model shows the beneficial effect of infliximab (anti-TNF-α) and other potential anti-cytokine therapies on the granuloma radius." (PMID 38550585, 2024). "Previous studies demonstrated that TNF-α played a crucial role in granuloma formation and maintenance, and thus control of tubercular infection." (PMID 38933114, 2024). "Subsequently, these macrophages release TNF-α, initiating the formation of granulomas, which represent the earliest defense mechanism against this pathogen." (PMID 39066368, 2024).
Granuloma (continued). "In sarcoidosis granulomas, monocyte-derived macrophages are activated by pro-inflammatory cytokines including TNF and IL-6." (PMID 39284999, 2024). "In immunohistochemistry analyses it has been described that TNF is expressed in epithelioid cell macrophages of PB and MB lesions and contributes to the formation of granulomas." (PMID 38381878, 2024). "Anti-TNF-α therapies have anti-granuloma effects and are already being used to successfully treat cutaneous non-infectious granulomatous diseases, including sarcoidosis and granuloma annulare." (PMID 38612420, 2024). "TNFα expression can increase in patients with sarcoidosis, thereby promoting the formation and maintenance of granulomas." (PMID 39279263, 2024). "Producing the pro-inflammatory cytokines IL-1β and TNF-α helps inhibit Mtb infection in granulomas and prevent the spread of Mtb." (PMID 37818041, 2023). "These cells secrete pro-inflammatory cytokines, including interferon-γ (IFN-γ), interleukin-2 (IL-2), and tumor necrosis factor-α (TNF-α), which mediate local granuloma development." (PMID 37062818, 2023). "Treatment with anti-tumor necrosis factor (TNF) agents in LTBI patients can favor granuloma development with subsequent growth of the mycobacterium." (PMID 37398734, 2023). "The data revealed elevated expression of IL-1β, IL-6, and TNF-α, all known to reflect the pathogenesis of sarcoidosis, in the in vitro granuloma model." (PMID 38038136, 2023). "Modulation of the host immune response by PPE17 leads to the release of the proinflammatory cytokine tumor necrosis factor-alpha (TNF-α), which is associated with granuloma formation in TB." (PMID 38162666, 2023). "TNF-α is a pro-inflammatory cytokine that plays an important role in the formation and maintenance of granulomas." (PMID 37998388, 2023). "Granuloma formation is in part promoted by cytokines such as tumor necrosis factor [TNF] as well as by cell death." (PMID 37200402, 2023). "An analysis of the granulomas showed that in chronic infection, the anti-TNF antibody penetrated the tissue deeper and was retained for an extended period of time as compared with the TNFR-2 fusion protein." (PMID 36358688, 2022). "TNF is a key cytokine involved in the formation and maintenance of granulomas during TB and the absence of TNF signaling results in disruption of granulomas and dissemination of bacteria." (PMID 35669122, 2022). "TNF-α is a crucial pro-inflammatory cytokine in the protective immune responses of host responsive to Mtb, and a considerable concentration of TNF-α is necessary for the formation of Mtb-induced granulomas." (PMID 35651754, 2022). "The presence of cytokines, to as IL-1β, IL-6 and TNF-a, suggest that these cytokines have a role in granuloma formation in to patients." (PMID 35672755, 2022). "Our data demonstrated that FBXW7 played a crucial role in the formation of Mtb-induced granulomas by altering the expression of cytokines especially the level of TNF-α for the mycobacterial survival in the host." (PMID 35651754, 2022). "Cytokines, such as IFN-γ and TNF-α, facilitate the formation and maintenance of granulomas; IFN-γ also enhances the macrophage function against the mycobacterium by increasing the levels of nitrosoglutathione (GSNO)." (PMID 35453358, 2022). "It is known that a subpopulation of CD56+ NK cells is activated and produces IFN-γ and TNF-α in sarcoidosis patients, implying involvement of these cells in granuloma formation." (PMID 36203777, 2022). "Cytokines such as IL-1β, IL-4 IL-5, IL-6, IL-13, TNF-α, MCP-1, and TSLP induce allergy-related inflammation, which causes tissue fibrosis, granuloma formation, and leukocyte infiltration." (PMID 36235405, 2022). "Both protein and mRNA of the proinflammatory cytokine TNF-α have been seen at variable levels in all granuloma stages, with a single study demonstrating an increasing trend from stage I through stage IV granulomas." (PMID 35056009, 2022).